MMP7 (matrix metallopeptidase 7)
Diseases named in the same sentence as MMP7 in open-access papers (continued):
Sharing a sentence is not in itself a finding about the gene and the disease.
chronic obstructive pulmonary disease (6 papers, 2013 to 2021). A chronic and progressive lung disorder characterized by the loss of elasticity of the bronchial tree and the air sacs, destruction of the air sacs wall, thickening of the bronchial wall, and mucous accumulation in the bronchial tree. "Similarly, patients diagnosed with IPF exhibit sex disparity in MMP-7 gene expression when compared to controls or to patients suffering from chronic obstructive pulmonary disease (COPD)." (PMID 34072833, 2021). "The assessment of MMP-7 activity is considered to be clinically important for patients with IPF, chronic obstructive pulmonary disease (COPD), small cell lung cancer, adenocarcinoma, and squamous cell carcinoma." (PMID 32053892, 2020).
Cirrhosis (6 papers, 2016 to 2026). A chronic disorder of the liver in which liver tissue becomes scarred and is partially replaced by regenerative nodules and fibrotic tissue resulting in loss of liver function. "MMP-7 is upregulated in biliary atresia-associated liver fibrosis, and its expression is considered the best strategy to distinguish between cirrhosis and pre-cirrhosis stages." (PMID 32630493, 2020). "For cirrhosis discrimination, MMP-7 achieved an area under the curve (AUC) of 0.830 (95% CI: 0.765-0.894); combining it with APRI/ FIB-4 did not significantly improve accuracy (combined AUC = 0.849, p = 0.224)." (PMID 42100283, 2026). "MMP7 was also a strong predictor of LSM ≥ 9.5 (advanced fibrosis) and LSM ≥ 13.0 (concerning for cirrhosis) in older patients." (PMID 33536476, 2021).
coronary disease (6 papers, 2014 to 2025). "While all mice harboured coronary disease, atherosclerotic burden was reduced in Mmp7-deficient and Mmp12-deficient mice and increased in Timp1-deficient animals, compared to relevant controls." (PMID 34848763, 2021). "In addition, at the protein level, plasma concentrations of MMP7 were increased in patients with coronary artery disease." (PMID 24628908, 2014). "The plasma levels of MMP-1, MMP-7, MMP-8, MMP-9, and MMP-10 are elevated in patients with coronary artery disease (CAD), whereas those of MMP-2 and MMP-3 levels are decreased." (PMID 36142454, 2022). "MMP‐7 was higher in those with coronary disease, whether or not they had a prior known MI, compared with the ‘no CAD/no MI’ group." (PMID 37939716, 2024). "MMP-7 levels were not significantly different in patients with and without coronary disease." (PMID 32101136, 2020).
endometrial cancer (6 papers, 2012 to 2025). Primary or metastatic malignant neoplasm involving the endometrium (mucous membrane that lines the endometrial cavity). "There are also reports indicating that LPA promoted endometrial cancer invasion via the induction of matrix metalloproteinase-7 (MMP-7)." (PMID 24744506, 2014). "Lef1 is overexpressed in both mouse and human endometrial cancer specimens, and certain Lef1 downstream targets are activated through this mechanism, specifically cyclin D1 and MMP7." (PMID 22792274, 2012). "The role of MMPs, especially MMP-7 and MMP-26, in the pathogenesis of endometrial cancer involves several related mechanisms." (PMID 40332487, 2025). "We investigated the levels of MMP-7, MMP-26, MMP-3, and MMP-10 in comparison with the levels of a tumor marker (CA125) in the plasma of postmenopausal patients in early stages of endometrial cancer (EC) compared with control groups: patients with benign lesions (myoma uteri) and healthy controls." (PMID 40332487, 2025). "Our discovery that the expression of both cyclin D1 and MMP7 was higher in endometrial tumors than in normal, non-cancerous endometrium is consistent with previous reports showing that both of these proteins are elevated in patients with endometrial cancer." (PMID 22792274, 2012).
inflammatory bowel disease (6 papers, 2015 to 2024). A spectrum of small and large bowel inflammatory diseases of unknown etiology. "Previous studies implicated matrix metalloproteinases (MMPs), such as MMP-7, in inflammatory bowel diseases (IBD) by showing increased activity during inflammation of the gut." (PMID 36275703, 2022). "In previous studies we demonstrated enhanced expression of tumor-associated MMPs (MMP-2, MMP-7, MMP-9, and MMP-13) in native, unfixed, but cryo-conserved samples of patients with inflammatory bowel disease by qRT-PCR, ELISA, and immunofluorescence." (PMID 27716617, 2016). "Literature data indicate that the main biomarkers of inflammatory bowel diseases are four MMPs, i.e., MMP-3, MMP-7, MMP-9, and MMP-11." (PMID 38203373, 2023). "MMP-7 and MMP-13, which are expressed primarily on the tumor cell surface, are elevated in inflammatory bowel disease." (PMID 27716617, 2016). "Moreover, it has been reported that MMPs, especially MMP-7 and MMP-13, which are expressed primarily on the tumor cell surface, are elevated in inflammatory bowel disease, which may have more chance to evolve into malignancy than normal tissue." (PMID 25742789, 2015).
intestinal tumor (6 papers, 2003 to 2022). "Previously, we demonstrated that MMP-7, a protease implicated in mammary and intestinal tumor growth, can process the adherens junction component E-cadherin." (PMID 20628524, 2010). "A number of different MMPs may be important in intestinal tumour formation as human tumours have been shown to express interstitial collagenase (MMP-1), gelatinase A (MMP-2), stromelysin 1 (MMP-3), matrilysin (MMP-7), gelatinase B (MMP-9), and stromelysin 3 (MMP-11)." (PMID 12778076, 2003).
periodontal disease (6 papers, 2022 to 2025). "This study suggests that MMP-7, EMMPRIN, and CypA are closely linked to the development and progression of periodontal disease, with their expression levels reflecting the degree of periodontal tissue destruction." (PMID 40075856, 2025).
squamous cell carcinoma (6 papers, 2013 to 2020). A carcinoma arising from squamous epithelial cells. "Although the specific mechanisms by which Rap1A mediates cell invasion are unclear, Rap1A has been shown to stimulate MMP-7 gene transcription in squamous cell carcinoma cells via β-catenin." (PMID 23405264, 2013). "The difference of MMP-7 protein expression between adenocarcinoma patients and squamous cell carcinoma patients has no obvious statistical significance whether by using SP or Non-SP (both P >0.05)." (PMID 25588786, 2015). "MMP7 and ALDH1A3, that are stem cell markers for squamous cell carcinoma, were not expressed in neither treated nor untreated tumors." (PMID 27716314, 2016).
chronic periodontitis (5 papers, 2019 to 2025). A chronic inflammatory process that affects the tissues that surround and support the teeth. "Mucin 4 (MUC4) and matrix metalloproteinase 7 (MMP7) have been reported to be associated with chronic periodontitis as seen in gingival tissue biopsies." (PMID 36518149, 2022).
colon adenocarcinoma (5 papers, 2016 to 2022). "Differences in the expression pattern of MMP7, MMP10 and MMP12 in 78 serum specimens of patients with an adenocarcinoma of the colon and serum specimens of a healthy control group were assessed using Luminex-100 technologies." (PMID 27431388, 2016).
colorectal adenocarcinoma (5 papers, 2015 to 2023). The most common type of colorectal carcinoma. "Up-regulation of MMP-7 occurs very early in colonic epithelial cells and has been found in 85% of colorectal adenocarcinomas and associated with a poor prognosis." (PMID 25596746, 2015). "HCT-116, HT-29 (a human-derived colorectal adenocarcinoma), FHC (a normal colon epithelial cell), and HEK 293 cell lines (widely known as the Human Embryonic Kidney 293 cells) were subjected to WBs using an anti-MMP-7 antibody." (PMID 36831488, 2023).
colorectal adenoma (5 papers, 2006 to 2025). An adenoma that arises from the colon or rectum. "To explore whether MMP1, MMP3 and MMP7 gene promoter polymorphisms are involved in the early step of colorectal carcinogenesis, we investigated the relation between these polymorphisms and the risk of colorectal adenoma in a case-control study." (PMID 17125518, 2006). "MMPs are overexpressed in a variety of premalignant tumor tissues, including colorectal adenoma and MMP7 has been shown to be important in the growth of early colonic adenomas and their transformation into invasive cancer." (PMID 17125518, 2006). "Using a fluorescent MMP-7 probe to detect colorectal adenomas in adenomatous polyposis coli (Apc)+/Min-FCCC mice that spontaneously develop colorectal adenomas, more than 92% of colon adenomas were identified, suggesting its potential use for early detection and intervention." (PMID 24518611, 2014).
Crohn disease (5 papers, 2016 to 2023). A gastrointestinal disorder characterized by chronic inflammation involving all layers of the intestinal wall, noncaseating granulomas affecting the intestinal wall and regional lymph nodes, and transmural fibrosis. "In addition, MMP-7 is a biomarker of Crohn’s disease as a differentiating marker for inflammatory tissues." (PMID 37895400, 2023). "Moreover, MMP-7 is a biomarker of Crohn’s disease as a marker differentiating inflammatory tissues." (PMID 38203373, 2023). "The most frequently analyzed metalloproteinases in Crohn’s disease are: MMP-1, MMP-3, MMP-7, MMP-8 and MMP-9." (PMID 37895443, 2023). "The aim of our study was to evaluate the expression of MMP-2, MMP-7, MMP-9, TIMP-1, and TIMP-2 in ulcerative colitis and Crohn's disease." (PMID 27034654, 2016). "MMP-1, MMP-3, MMP-7, MMP-8 and MMP-9 are biomarkers of Crohn’s disease." (PMID 37895400, 2023). "To verify the therapeutic effect of MMP-7 blockade, we administered MMP-7 antibody in rats subjected to repeat insult of TNBS, which develop transmural inflammation resembling the histopathological lesions found in human Crohn’s disease (top)." (PMID 36275703, 2022).
emphysema (5 papers, 2009 to 2022). "MMP-3 and -10 had significant associations with all forms of emphysema (apart from mild CLE) while MMP-7, -8 and -9 had associations with multiple sub-types." (PMID 27460105, 2016). "In particular, emphysema defined by parenchymal voxels with computed attenuation values less than −950 Hounsfield Units (HU) was associated with higher blood levels of IL-6 and MMP-7, but lower TNFα levels." (PMID 23577098, 2013). "MMP-3, and -10 associated with all emphysema sub-types other than mild CLE, while MMP-7 and -8 had associations with moderate and severe CLE and PSE." (PMID 27460105, 2016). "While IL-6 and MMP-7 were directly associated with F-950, TNF-α was inversely related to emphysema severity." (PMID 19718453, 2009). "Three of the 33 inflammatory markers, IL-6, MMP-7 and tumor necrosis factor alpha (TNF-α), were associated with quantitative emphysema." (PMID 19718453, 2009).
endometriosis (5 papers, 2019 to 2025). The growth of functional endometrial tissue in anatomic sites outside the uterine body. "MMP9 and MMP7 showed strong discrimination for adenomyosis vs. endometriosis [area under the curve (AUC) = 0.93] and co-existent cases (AUC = 0.97), respectively." (PMID 41272701, 2025). "It is important to mention that MMP7 outperformed the other genes in distinguishing adenomyosis from co-existent adenomyosis–endometriosis (AUC = 0.97)." (PMID 41272701, 2025). "Compared to those with I/II endometriosis, increased mean gene expression in endometriotic tissue from women with III/IV endometriosis was observed for MMP7 (0.10 vs. 0.00), FUT8 (1.14 vs. 0.02), and SOX2 (1.51 vs. 0.36)." (PMID 38674005, 2024). "Together, these findings suggest that endometriosis is immune and uterine specific and that MMP7 likely plays a role in the ability of uterine tissue and the innate immune system to establish and maintain endometriotic lesions." (PMID 34975547, 2021). "In contrast, on comparing adenomyosis with the co-existent adenomyosis–endometriosis group, MMP7 demonstrated the highest discriminatory power (AUC = 0.97, p < 0.0001), indicating its potential as a key marker for distinguishing isolated adenomyosis from overlapping pathology." (PMID 41272701, 2025). "Interestingly, MMP7 expression was observed to be the highest in the co-existent adenomyosis–endometriosis group, suggesting a synergistic effect on ECM degradation in the presence of dual pathology, potentially driving more aggressive tissue remodeling." (PMID 41272701, 2025). "MMP7, MMP9, MMP11, and TIMP1 were observed to be significantly upregulated in women with adenomyosis as compared to endometriosis." (PMID 41272701, 2025). "Out of these, significant overexpression of MMP7, MMP9, MMP11, IGFBP5, and TIMP1 was observed at both gene and protein levels in adenomyosis as compared to endometriosis." (PMID 41272701, 2025). "MMP-7 and MMP-26 are usually expressed in healthy female endometria and in various uterine lesions, such as endometriosis and myomas." (PMID 40332487, 2025). "Next, topological analysis using the cytoHubba plugin in Cytoscape identified MMP7, MMP11, SERPINA1, THBS1, and IGFBP5 as candidate hub genes expressed in both adenomyosis and endometriosis." (PMID 41272701, 2025).
gastritis (5 papers, 2010 to 2025). Inflammation of the stomach. "MMP-7, which was found to be upregulated in epithelium in the case of H. pylori–associated gastritis, contributes to gastric carcinogenesis." (PMID 35163805, 2022). "The objective of this study was to investigate the serum levels of IL-10, MMP-7 & MMP-9 in gastritis patients with H. pylori infection." (PMID 27703556, 2016). "However, another group has demonstrated the protective role of MMP-7 in H. pylori–related gastritis (and carcinogenesis) in vivo." (PMID 35163805, 2022). "Serum levels of MMP-9 (but not MMP-3 and MMP-7) were also higher in patients with H. pylori–associated gastric ulcer in comparison to those of patients with H. pylori–positive gastritis and cancer." (PMID 35163805, 2022). "In adults with H. pylori–related gastritis, increased levels of MMP-8 and -9, an unchanged level of MMP-7 and decreased levels of MMP-2 and TIMP-1 in comparison to healthy volunteers were detected in serum by using ELISA." (PMID 35163805, 2022). "pylori-infected patients enrolled, 470 patients (265 with gastritis, 118 with duodenal ulcer, and 87 with gastric ulcer) received SNPs analysis of MMP-3-1612 6A > 5A, MMP-7-181 A > G, MMP-9exon 6 A > G, TIMP-1372 T > C and TIMP-2-418 G > C by PCR-RFLP." (PMID 20707923, 2010). "In this study, the objective is to evaluate the increase of IL-10, MMP-7 and MMP-9 in patients with H. pylori infection without any systemic disease and the correlation with the histopathologic degree of gastritis." (PMID 27703556, 2016).
kidney damage (5 papers, 2020 to 2025). "MMP-7 urine excretion appears to be a better indicator than serum MMP-7 in patients with kidney damage, despite their diabetic record." (PMID 40026998, 2025). "In particular, Mmp7, Mmp10, and Mmp12 were highlighted for their differential expression between strains and their potential role in influencing the severity of kidney damage." (PMID 38674390, 2024). "In summary, evidence for MMP-7 as a biomarker for kidney damage is present and has increased in the last 5 years." (PMID 37298105, 2023). "Unfortunately, only singular observations, such as MMP-7 as a serum marker for kidney damage and a recent study proposing it as an early urinary biomarker for kidney decline in hypertensive patients, have been made." (PMID 37298105, 2023). "As to the cues responsible for MMP-7 induction in vivo, many studies have pointed to Wnt/β-catenin signaling, which is activated in virtually every kind of nephropathy." (PMID 32630493, 2020). "The first evidence that MMP-7 might play a role in tubular damage and thus be a candidate biomarker for kidney damage was collected in 2004." (PMID 37298105, 2023). "Increased mRNA tissue expression of MMP-7 has been observed in embryological development of congenital renal dysplasia, chronic renal allograft rejection, as well as drug-induced nephropathy and obstructive uropathy via increased Wnt-beta catenin activity." (PMID 35834547, 2022). "Although the specific action of MMP-7 in different nephropathy models has not been fully clarified, numerous studies have discovered discrete roles of MMP-7 in renal pathophysiology in different settings." (PMID 32630493, 2020).
renal cell carcinoma (5 papers, 2011 to 2026). "First, CD34, an endothelial progenitor biomarker, was discovered in renal cell carcinoma expressing MMP7, suggesting that MMP7 may contribute to tumourigenesis by correlating with tumour-induced neovascularization." (PMID 31937294, 2020). "The expression of MMP-7 is, however, induced in a wide variety of kidney diseases, including AKI, CKD, glomerular disease, inherited kidney disease, and renal cell carcinoma, suggesting that MMP-7 induction is a common feature of the kidney after various injuries." (PMID 32630493, 2020). "We focus on the specific role of MMP2, MMP7, and MMP9 in clear cell renal cell carcinoma (ccRCC) and major subtypes of RCC." (PMID 41893368, 2026).